BAAT (bile acid-CoA:amino acid N-acyltransferase)
Description:
Catalyzes the amidation of bile acids (BAs) with the amino acids taurine and glycine. More than 95% of the BAs are N-acyl amidates with glycine and taurine. Amidation of BAs in the liver with glycine or taurine prior to their excretion into bile is an important biochemical event in bile acid metabolism. This conjugation (or amidation) plays several important biological roles in that it promotes the secretion of BAs and cholesterol into bile and increases the detergent properties of BAs in the intestine, which facilitates lipid and vitamin absorption. May also act as an acyl-CoA thioesterase that regulates intracellular levels of free fatty acids. In vitro, catalyzes the hydrolysis of long- and very long-chain saturated acyl-CoAs to the free fatty acid and coenzyme A (CoASH), and conjugates glycine to these acyl-CoAs.
Synonyms: BACAT; BAT; BACD1; FHCA3; HCHO
Tractability: PROTAC: its protein half-life has been measured.
Gene: Protein-coding gene on chromosome 9 (101,354,182 to 101,385,400, reverse strand). Ensembl gene ENSG00000136881.
Subcellular location: Cytoplasm, cytosol; Peroxisome
Subcellular location (Human Protein Atlas): Vesicles; Cytosol
Pathways (Reactome):
Metabolism: Recycling of bile acids and salts; Synthesis of bile acids and bile salts via 7alpha-hydroxycholesterol
Protein localization: Peroxisomal protein import
Gene Ontology:
Molecular function: acyltransferase activity, transferring groups other than amino-acyl groups; choloyl-CoA hydrolase activity; glycine N-choloyltransferase activity; long-chain fatty acyl-CoA hydrolase activity; medium-chain fatty acyl-CoA hydrolase activity; protein binding; very long-chain fatty acyl-CoA hydrolase activity; acyltransferase activity; fatty acyl-CoA hydrolase activity; acyl-CoA hydrolase activity; glycine N-acyltransferase activity; thiolester hydrolase activity
Biological process: acyl-CoA metabolic process; bile acid biosynthetic process; bile acid conjugation; glycine metabolic process; taurine metabolic process; bile acid metabolic process; fatty acid metabolic process; animal organ regeneration; lipid metabolic process; liver development; monocarboxylic acid metabolic process
Cellular component: cytosol; peroxisome; peroxisomal matrix
Genetic constraint (gnomAD): Loss-of-function variants: 15 observed, 22.02 expected, observed/expected ratio (o/e) 0.68, 90% interval 0.46 to 1.05. The upper end of that interval is the gene's LOEUF score, 1.05, which puts it in group 4 of 6, group 1 being the genes least tolerant of losing a copy. Missense variants: 489 observed, 529.86 expected, observed/expected ratio (o/e) 0.92, 90% interval 0.86 to 1. Synonymous variants: 170 observed, 201.39 expected, observed/expected ratio (o/e) 0.84, 90% interval 0.74 to 0.96.
Homologues: Orthologues: chimpanzee BAAT (98% identical), macaque BAAT (91% identical), dog BAAT (72% identical), rat Baat (70% identical), mouse Baat (69% identical), guinea pig BAAT (69% identical), pig BAAT (66% identical), tropical clawed frog baat (47% identical), Caenorhabditis elegans W03D8.8 (27% identical), Caenorhabditis elegans C31H5.6 (26% identical), Caenorhabditis elegans K05B2.4 (26% identical), Caenorhabditis elegans T05E7.1 (25% identical). Paralogues in human: ACOT1 (45% identical), ACOT2 (45% identical), ACOT4 (45% identical), ACOT6 (42% identical).
Diseases named in the same sentence as BAAT in open-access papers:
BAAT is named in the same sentence as 21 diseases in open-access papers, as found by Europe PMC text mining. Sharing a sentence is not in itself a finding about the gene and the disease. The quoted sentences say what the papers report.
cholestasis (8 papers, 2012 to 2025). Impairment of the bile flow caused by obstruction within the liver, or outside the liver in the bile duct system. "Loss of function of BAAT in humans leads to cholestasis in children and poor fat and fat-soluble vitamin absorption." (PMID 36958721, 2023). "For example, dysregulation or mutations in genes encoding for bile salt export pump (BSEP), multidrug resistance protein 3 (MDR3), or cholesterol 7a-hydroxylase (CYP7A1) and bile acid-CoA:amino acid N-acyltransferease (BAAT) can evoke cholestasis." (PMID 24112857, 2013). "CSA, a well-known inducer of cholestasis, downregulated gene expression of CYP7A1, CYP27A1, BAAT, HNF4A, and INSIG1, while it upregulated ACAT2 and CCL20 gene expression." (PMID 38953992, 2024).
Sepsis (2 papers, 2012 to 2025). Sepsis is defined as life-threatening organ dysfunction caused by a dysregulated host response to infection. "Compared to septic wild types, BAAT expression was maintained in the peroxisomal fraction and increased in the cytosolic fraction in PI3Kγ−/− mice 6 h after sepsis induction." (PMID 23152722, 2012). "BAAT immunoreactive protein levels were diminished by approximately 60% and 40% within the cytosolic and peroxisomal fractions, respectively, at 15 h after sepsis induction." (PMID 23152722, 2012). "Despite higher levels of circulating cytokines, BAAT expression in hepatocytes was preserved or increased in PI3Kγ−/− mice 6 h post-sepsis compared to wild-type septic controls, suggesting that BAAT may be a downstream target of PI3Kγ signalling." (PMID 23152722, 2012).
liver cancer (1 paper, 2025). An epithelial or non-epithelial malignant neoplasm that arises from the liver. "In contrast, the Matrigel group showed higher expression of genes with indirect relevance to liver cancer, such as bile acid-CoA amino acid N-acyltransferase (BAAT), which plays a role in bile acid production." (PMID 40852642, 2025).
pulmonary fibrosis (1 paper, 2025). Chronic progressive interstitial lung disorder characterized by the replacement of the lung tissue by connective tissue, leading to progressive dyspnea, respiratory failure, or right heart failure. "We propose that the enzyme encoded by BAAT may exhibit catalytic activity in the lung and contribute to pulmonary fibrosis through several potential mechanisms:1." (PMID 40857336, 2025).
cancer (5 papers, 2019 to 2025). A tumor composed of atypical neoplastic, often pleomorphic cells that invade other tissues. "We also identified bile acid-CoA:amino acid N-acyltransferase (BAAT) by gene set enrichment analysis, which dominates the final step in the synthesis of conjugated bile acids associated with the inflammatory-cancer transformation process." (PMID 36901689, 2023). "FN1 overexpression can trigger ER stress and facilitate lipid accumulation, while BAAT transcription in conjugation with glycine or taurine regulates cholesterol and phospholipid synthesis, favoring cancer growth." (PMID 35626705, 2022).
tumor (4 papers, 2022 to 2025). "The study has shown that knocking out BAAT inhibits the synthesis of conjugated BAs in hepatocytes, enhances tumor-specific T cell responses, inhibits tumor growth, and increases tumor sensitivity to immunotherapy." (PMID 40980688, 2025). "The activities of CA1, ANXA10, and MUC1 were increased in LPS treated IBD enteroids compared to the LPS treated tumor enteroids, while the activities of BAAT, ACSL5, and ENPP6 were decreased." (PMID 35884586, 2022). "Inhibition of taurine transporter abrogated the tumor-promoting effects of the bile acid synthesis enzymes CYP7A1 and BAAT." (PMID 41590614, 2025). "Elevated levels of the bile acid–conjugating enzyme BAAT (bile acid-CoA:amino acid N-acyltransferase) were found in HCC patients, with its deletion in mice leading to enhanced tumor-specific T cell responses and reduced tumor growth." (PMID 40181829, 2025). "The peroxisomal metabolic gene, BAAT, was found to be among the top DEGs in both the IBD intestinal organoids and tumor enteroids." (PMID 35884586, 2022).
skeletal dysplasia (1 paper, 2024). Any Mendelian diseases that affects growth and development of the skeleton. "In this study, we reported a novel homozygous frameshift mutation (c.388dupA, p.R130Kfs*12) in the BAAT gene of a female child diagnosed with skeletal dysplasia." (PMID 39252318, 2024). "This research reported a case of skeletal dysplasia caused by a frameshift mutation in the BAAT gene." (PMID 39252318, 2024).
BAAT also shares sentences with these, for which no sentence is quoted: breast carcinoma (2 papers); leukemia (2); Obesity (2); brain disorder (1); colorectal cancer (1); depression (1); Failure to thrive (1); lymphedema (1); lymphoma (1); myocardial infarction (1); neurological diseases (1); parathyroid tumor (1); steatosis (1); vitamin deficiency (1).